BRCA1 (BRCA1 DNA repair associated)
Diseases named in the same sentence as BRCA1 in open-access papers (continued):
Sharing a sentence is not in itself a finding about the gene and the disease.
breast cancer (continued). "In another study, BRCA1 recruits GATA3 to the FOXC1 promoter to repress its expression in normal breast cells, inhibiting the development of the BLBC subtype of breast cancer." (PMID 30764547, 2019). "In breast cancer, lncRNA NBR2 (neighbour of BRCA1 gene 2) overexpression upregulates GLUT1 expression through stimulating AMPK activity." (PMID 30499165, 2019). "In summary, our findings reveal that BRCA1 modulates aspartate biosynthesis through transcriptional repression of GOT2, and provides a biological basis for treatment choices in breast cancer." (PMID 30714292, 2019). "This quality improvement study and cost-effectiveness analysis evaluates mainstream genetic testing using cancer-based criteria to determine eligibility for BRCA1 and BRCA2 testing in patients with breast cancer." (PMID 31125106, 2019). "During the onset of carcinogenesis, shifted splicing of DNA repair genes has previously been documented in several cancer studies, such as BRCA1 and FANCM in breast cancer and ERCC1 in ovarian cancer." (PMID 31636653, 2019). "Therefore, further validation in study populations consisting of higher proportion of BRCA1- and BRCA2-deficient breast cancers, such as that in breast cancer cohorts enriched with a prior high-risk patients, may be warranted to assess the generalizability of our findings." (PMID 31022191, 2019). "Finally, we sought to define whether PALB2-associated breast cancers with bi-allelic PALB2 inactivation would differ from breast cancers arising in BRCA1 and BRCA2 pathogenic germline mutation carriers with bi-allelic inactivation of BRCA1 and BRCA2, respectively." (PMID 31428676, 2019). "The National Comprehensive Cancer Network (NCCN) guidelines for genetic assessment in hereditary breast cancer (version 3.2019) recommends genetic evaluation of ATM, CDH1, CHEK2, NBN, NF1, and PALB2 in addition to BRCA1/2 genes." (PMID 31658756, 2019). "In plasma membrane of breast cancer cells, 25 proteins get 27 N-glycosylation sites, such as BRCA-1, CD44, EGFR, can influence invasion and metastasis of breast cancer by regulating differentiation and proliferation of tumor cells." (PMID 31341840, 2019). "Consistent with previous reports in breast cancer cells, we found that E2F1 depletion reduced BRCA1 expression in MDA-MB-231 cells." (PMID 31604914, 2019). "Module 3 (4 genes) included regulation of cellular response to stress (BRCA1, CTNNB1, HSP90AA1, and WNT1) and breast cancer (BRCA1, CTNNB1, and WNT1)." (PMID 31608105, 2019). "Collectively, these findings demonstrated the correlation between BRCA1/ZBRK1 and GOT2 in breast cancer samples and suggested the promising prognostic value of GOT2 in clinical practice." (PMID 30714292, 2019). "The interactions between T cell activation status and either BRCA1 or CCND1 expression were evaluated using Kaplan-Meier survival curves and multivariate Cox regression models in a public dataset with 1088 breast cancer patients." (PMID 31023256, 2019). "Genes such as BRCA1 and BRCA2 are even named after particular subtypes of breast cancer, indicating their unequivocal genetic contribution." (PMID 31480430, 2019). "In this multicenter, retrospective, matched cohort study, we investigated whether women with an inherited mutation in BRCA1 or BRCA2 experience more severe hematologic toxicities during curative intent chemotherapy for breast cancer than similar women without a mutation." (PMID 31407530, 2019). "This correlation was also observed in breast cancer, consistent with our observations that ZC3H18 regulates BRCA1 in breast cancer cells." (PMID 31604914, 2019).
breast cancer (continued). "Pre-pubertal GEN exposure (500 ppm) was shown to increase Brca1 expression and decrease DMBA-induced mammary tumor incidence and aggressiveness in mice." (PMID 31652854, 2019). "Despite the different roles of E2F1 in ovarian and breast cancer cells, ZC3H18 depletion reduced BRCA1 levels in both cell lines." (PMID 31604914, 2019). "This approach could help identify more patients with hereditary cancers; approximately 9% of patients with breast cancer who had tested negative for BRCA1/2 mutations and underwent subsequent panel testing were found to have a pathogenic mutation in a breast cancer susceptibility gene." (PMID 31083288, 2019). "In a large study, they found that for BRCA1 PV carriers, the PRS model that predicted ER-negative breast cancers was more predictive than the overall breast cancer model that was more predictive in BRCA2 PV carriers." (PMID 30832243, 2019). "The link between BRCA1 and EMT in breast cancer has been demonstrated, but so far it has not been investigated in ovarian cancer." (PMID 31213009, 2019). "In addition, it should be noted that the B-RSTTM was developed and validated as a tool to identify individuals at increased risk for BRCA1/2 mutations and it does not incorporate other breast cancer risk factors (e.g., smoking, alcohol consumption, age at menarche, age at first live birth of child)." (PMID 31270367, 2019). "Although the pathological features of BRCA1 breast cancer and BRCA2 breast cancer reported in our study were similar to that of Western studies, the rate of triple-negative breast cancer was very high (89%) in the BRCA1 L63X mutation group." (PMID 31143373, 2019). "BRCA1 (breast cancer, early onset 1) and BRCA2 (breast cancer, early onset 2) are essential components of the homologous recombination (HR) DNA repair machinery, which repairs toxic DNA double‐stranded breaks (DSBs)." (PMID 31529615, 2019). "Therefore, it is conceivable that genomic instability mediated by deficiency in BRCA1 and BRCA2 may give rise to immunophenotype in breast cancer predictive of response to immunotherapy such as increased expression of PD-L1 and PD-1 and higher abundance of tumour-infiltrating immune cells." (PMID 31022191, 2019). "Estimates are that about 1.1–1.7% of women with breast cancer have a PV in CHEK2, 1.4–2.1% in BRCA1, 1.6–2.2% in BRCA2, 0.87–1% in ATM, and 0.84–0.87% in PALB2, with other genes less than 1%." (PMID 30832243, 2019). "The higher incidence of breast cancer in the biobank population was likely a reflection of frequency of care and age; however, in our risk analysis, we used the biobank patients without evidence of BRCA1/2 variants as the control population, which mitigated this bias." (PMID 30646163, 2018). "Given our findings that BRCA1 loss results in PIN1 upregulation, we hypothesized that even in sporadic breast cancers not linked to germline BRCA1 mutation but that have low BRCA1 levels through other mechanisms, levels of BRCA1 and PIN1 expression would be inversely correlated." (PMID 30590041, 2018). "The prevalence of BRCA mutations varies in different Asian cohorts, with 21.7% (BRCA1 9.3%; BRCA2 12.4%) in patients with family history of breast or ovarian cancer in Korea and 17% (BRCA1 11%; BRCA2 6%) in Malaysian patients with early onset of breast cancer." (PMID 29861850, 2018). "Female BRCA1 and BRCA2 carriers from North West England were assessed for breast cancer incidence prior to 50 years of age comparing those with an early first full-term pregnancy (< 21 years) to those without a full-term pregnancy." (PMID 29116468, 2018). "After two decades since the discovery of the BRCA1 and BRCA2 genes, genetic testing for hereditary breast and ovarian cancer (HBOC) has become a standard practice for breast cancer patients." (PMID 30001421, 2018). "BRCA1 siRNA 1 and siRNA 2 targeting different sequences of the BRCA1 gene, reduced ACCA phosphorylation and increased FASN abundance in both MCF7 and T47D breast cancer cells." (PMID 30323899, 2018).
breast cancer (continued). "For example, inhibiting eIF4G1 delays resolution of DNA double-strand breaks in breast cancer cells by reducing CHK1, CHK2, and BRCA1 levels." (PMID 30382096, 2018). "BRCA1 and BRCA2 are widely recognized as caretaker genes for the genome and tumor suppressor genes for breast cancer." (PMID 29321957, 2018). "In contrast, BRCA1 was predominantly localised in the cytoplasm of MCF7 and T47D breast cancer cells which are ER-positive." (PMID 30323899, 2018). "Unfortunately, access to magnetic resonance imaging screening only became available for BRCA1 or BRCA2 carriers and women with a medical history of breast cancer half way through the study." (PMID 29318406, 2018). "Treatment of breast cancer cells with resveratrol increased acetylation of H3 and H4 decreased methylation of H3K9 and recruited MBD2 to the BRCA-1 promoter." (PMID 30627525, 2018). "For instance, an eight gene promoter hypermethylation panel (APC, BRCA1, BIN1, CST6, GSTP1, P16, P21, and TIMP3) had a reported sensitivity of 90% for identifying breast cancer patients." (PMID 29614786, 2018). "Interestingly, we identified 3 BRCA1 mutations (c.4046_4047delinsA, c.212+3A>G and c.5335delC) by NGS, which were novel to our Chinese BRCA1/2 mutation spectrum and were only seen in ovarian cancer cases, but not in the breast cancer cases in the present cohort." (PMID 29487695, 2018). "Here, we report that tamoxifen-resistant breast cancer cells express significantly more BARD1 and BRCA1, leading to resistance to DNA-damaging chemotherapy including cisplatin and adriamycin, but not to paclitaxel." (PMID 29686231, 2018). "In patients with BRCA1- and BRCA2-positive breast cancer, ovarian cryopreservation appears to be possible." (PMID 29177593, 2018). "Moreover, POFT cancer women with breast cancer as the SPC might have a higher possibility of BRCA1 or BRCA2 germline mutation compared to women without breast cancer." (PMID 30089478, 2018). "This study's aim was to identify MBD2 as biomarker which regulate the BRCA1 and p16 gene expression in MCF‐7 breast cancer cells by Real Time PCR." (PMID 29460395, 2018). "Gene-panel testing of BRCA1, BRCA2, PALB2 and RNASEL in the Australian Breast Cancer Family Registry identified five carriers of RNASEL:p.Glu265* in 591 early onset breast cancer cases." (PMID 29422015, 2018). "To address the role of mitochondria in the BRCA1-mediated metabolic rewiring of breast cancer, we compared the mitochondrial proteome of sporadic breast cancer cells (MCF7) with hereditary breast cancer cells." (PMID 29584711, 2018). "We manipulated BRCA1 expression using tetracycline in the UBR60-bcl2 cell line (which has an inducible, tetracycline-regulated BRCA1 expression) and siRNA in oestrogen receptor(ER)-positive MCF7 and T47D breast cancer cells." (PMID 30323899, 2018). "It has been shown, that triple negative cancers have reduced expression of NER, Fanconi Anemia pathways genes, RRM1, BRCA1 and CHK1 gene when compared to other types of breast cancers." (PMID 29507678, 2018).
breast cancer (continued). "Because many of the BRCA1/2 mutation carriers in our cohort had undergone prophylactic surgery after inclusion in the study, there were too few cases of breast cancer for a meaningful comparison of the breast cancer risk between current smokers and non-smokers." (PMID 29299723, 2018). "In BRCA1-dysfunctional breast cancers, LYN activity is upregulated by a prolyl isomerase (PIN1) that is normally repressed by BRCA1." (PMID 30590041, 2018). "In triple-negative breast cancer, in BRCA1-positive breast cancer, and in small HER2-positive breast cancers, the relationship between tumour size and survival is much attenuated, and for these women, tumour size is a very poor predictor of survival." (PMID 29353366, 2018). "We offered genetic testing of BRCA1 and BRCA2 to > 800 patients with newly diagnosed breast cancer and provided written pre-test information instead of in-person pre-test genetic counseling." (PMID 29164420, 2018). "Functional antagonism between BRCA1 and COBRA1 in R-loop regulation can be recapitulated in human breast cancer cells in vitro." (PMID 30558184, 2018). "Similar results are available for other cancer genes, such as BRAF in melanoma, BRCA1 and PIK3CA in breast cancer." (PMID 29485617, 2018). "Analysis of transcriptome data sets from TCGA (The cancer genome atlas) using Oncomine and cBioPortal, confirmed the inverse correlation between BRCA1 and CCL5/ Moesin in breast cancer." (PMID 30224826, 2018). "Rescue of the BRCA1-mutant breast cancer cell line, HCC1937, with overexpression of a full-length BRCA1 gene resulted in a significant increase in expression of miR-29b-1-5p." (PMID 30323900, 2018). "However, given that the majority of tumours that develop in BRCA1 mutation carriers are oestrogen receptor (ER)-negative, it seems counterintuitive that SERMs will reduce breast cancer risk, given that no benefit in ER-negative tumours has been shown in the chemoprevention setting with tamoxifen." (PMID 30580266, 2018). "Among the 73 BRCA1/2MUT+ carriers who underwent BCS, 3 were found to have ipsilateral breast cancer." (PMID 30203341, 2018). "Future studies should seek to evaluate whether rs1799950, and other common BRCA1 and BRCA2 variants, modulate sensitivity to platinum and other DNA damaging agents in vitro, and address whether such variants convey inherited susceptibility to malignancy, particularly to OC and breast carcinoma." (PMID 29298688, 2018). "Based on the roles of PARP1, γH2AX, BRCA1, and BRCA2 in DNA damage repair, the combined expression patterns were evaluated in breast carcinoma and soft tissue sarcomas." (PMID 29784019, 2018). "Although medullary and metaplastic breast carcinomas, with which ACC shares immunohistochemical and molecular findings, show a frequent promotor methylation of BRCA1 gene, ACC of the breast usually retains normal BRCA1 gene function." (PMID 30189404, 2018). "The spatial localization of BRCA1, BRCA2, RAD51, agrees with the known specificity of these genes to breast cancer, and physical or predicted interactions with each other." (PMID 28326099, 2017). "Risk prediction models assess either: group odds of developing breast cancer over time as BCRAT (Gail) model, or individual risks of inheriting a mutant BRCA1/2like BRCAPRO, BOADICEA, and the Myriad II prevalence tables." (PMID 28962650, 2017).
breast cancer (continued). "The OR estimate for male breast cancer per standard deviation (SD) increase in overall PRS was estimated to be 1.36 (95% CI, 1.19 to 1.56; P = 8.6 × 10−6) in combined BRCA1/2 carriers." (PMID 28448241, 2017). "Finally, 111 female BRCA1/2 mutation carriers who had not undergone risk-reducing surgery (i.e., salpingo oophorectomy) participated in a screening program involving both annual breast cancer screening and OC screening involving both CA125 testing and TVS." (PMID 28282847, 2017). "Forth, we recently showed that BRCA1-IRIS overexpression in fact initiates and maintains the tumor initiating phenotype in breast cancer cells." (PMID 28499366, 2017). "Previous reports demonstrated that FRK suppresses cell proliferation in breast cancer by various mechanisms, which include the stabilization of PTEN and BRCA1 and the internalization of EGFR." (PMID 29348886, 2017). "For instance, knockdown of BRCA2 in breast cancer cell lines modulated expression of RXR isoforms in opposing ways and knockout of BRCA1 reduced expression of PPARγ in cardiomyocytes." (PMID 28427429, 2017). "In addition, we identified multiple types of tumor suppressor gene (RB1 and BRCA1) mutations in both ovarian and breast cancer networks, which is consistent with findings that mutations in RB1 and BRCA1 are extremely important in the progression of ovarian and breast cancers." (PMID 28765560, 2017). "Since then, the screening of BRCA1 and BRCA2 has been performed in multiple populations across the world revealing that 10 to 50% of breast cancer patients with family history of breast and/or ovarian cancer carry a BRCA1 or BRCA2 mutation." (PMID 29088781, 2017). "Approximately 5–10% of all of breast and ovarian cancer cases reflect inherited genetic defects primarily in two well-known high-penetrance breast and ovarian cancer genes, BRCA1 (breast cancer 1, early onset) and BRCA2 (breast cancer 2, early onset)." (PMID 28738860, 2017). "That patient was BRCA1 and BRCA2 WT and had a personal history of bilateral breast cancer (diagnosed at 37 and 41 years old), both tumors were invasive ductal carcinomas with estrogen receptor negative." (PMID 27926510, 2017). "Further, human breast cancer tissue samples (n=3831) were analyzed using three cBioportal TCGA data sets, in which the expression levels of CGB5, CGB7 and BRCA1 were available." (PMID 28869585, 2017). "In Chile, our group has screened BRCA1 and BRCA2 genes in 336 patients with a family history of breast cancer and 117 patients unselected for family history, recruited throughout the country." (PMID 29088781, 2017). "(2011) reported c‐MYC‐mediated BRCA1 promoter activation, an essential component of HRR in breast cancer, which influenced I‐SceI‐induced HRR." (PMID 28173629, 2017). "We also confirmed the therapeutic effect of the combination of olaparib and 4OH-TAM in ER+ breast cancer cells, CAMA-1 and ZR75-1 that had WT BRCA1 and were resistant to olaparib." (PMID 28968398, 2017). "Previous studies attempted to discriminate BRCA1/2, non-BRCA1/2 (BRCAX) and sporadic breast cancers were based on gene expression levels and histological tests performed on breast tumor tissue." (PMID 29108258, 2017). "In this study, we evaluated the antioxidant potential and the influence of pitaya extract (PE) on cell viability, colony formation, cell cycle, apoptosis, and expression of BRCA1, BRCA2, PRAB, and Erα in breast cancer cell lines (MCF-7 and MDA-MB-435)." (PMID 28761624, 2017). "In another study, Romagnolo and coworkers used MCF-7 breast cancer cells and reported that RVT was able to reduce DNMT1 activity at the BRCA-1 promoter." (PMID 29104258, 2017). "However, neither VDR nor RXR nor PPARγ have been studied in BRCA1 associated breast cancer so far." (PMID 28427429, 2017).